CRTC2 (CREB regulated transcription coactivator 2)
Description:
Transcriptional coactivator for CREB1 which activates transcription through both consensus and variant cAMP response element (CRE) sites. Acts as a coactivator, in the SIK/TORC signaling pathway, being active when dephosphorylated and acts independently of CREB1 'Ser-133' phosphorylation. Enhances the interaction of CREB1 with TAF4. Regulates gluconeogenesis as a component of the LKB1/AMPK/TORC2 signaling pathway. Regulates the expression of specific genes such as the steroidogenic gene, StAR. Potent coactivator of PPARGC1A and inducer of mitochondrial biogenesis in muscle cells. Also coactivator for TAX activation of the human T-cell leukemia virus type 1 (HTLV-1) long terminal repeats (LTR).
Synonyms: TORC-2; TORC2
Tractability: PROTAC: UniProt records ubiquitination sites on it; ubiquitination databases record sites on it; its protein half-life has been measured.
Safety:
Unwanted effects reported when the protein is acted on. In parentheses: how it was acted on, where the effect was seen, and who reports it.
new-onset diabetes after transplantation (NODAT) (source: ClinPGx)
Gene: Protein-coding gene on chromosome 1 (153,947,669 to 153,958,634, reverse strand). Ensembl gene ENSG00000160741.
Subcellular location: Cytoplasm; Nucleus
Subcellular location (Human Protein Atlas): Nucleoplasm
Pathways (Reactome):
Cellular responses to stimuli: Heme signaling
Circadian clock: Expression of BMAL (ARNTL), CLOCK, and NPAS2
Organelle biogenesis and maintenance: Transcriptional activation of mitochondrial biogenesis
Gene Ontology:
Molecular function: protein binding; cAMP response element binding protein binding; transcription coactivator activity
Biological process: cellular response to cAMP; gluconeogenesis; glucose homeostasis; positive regulation of transcription by RNA polymerase II; protein homotetramerization
Cellular component: cytoplasm; extracellular exosome; nucleoplasm; nucleus
Genetic constraint (gnomAD): Loss-of-function variants: 25 observed, 69.57 expected, observed/expected ratio (o/e) 0.36, 90% interval 0.26 to 0.5. The upper end of that interval is the gene's LOEUF score, 0.5, which puts it in group 2 of 6, group 1 being the genes least tolerant of losing a copy. Missense variants: 730 observed, 906.02 expected, observed/expected ratio (o/e) 0.81, 90% interval 0.76 to 0.86. Synonymous variants: 329 observed, 381.61 expected, observed/expected ratio (o/e) 0.86, 90% interval 0.79 to 0.94.
Homologues: Orthologues: macaque CRTC2 (99% identical), chimpanzee CRTC2 (96% identical), pig CRTC2 (94% identical), mouse Crtc2 (92% identical), rat Crtc2 (92% identical), guinea pig CRTC2 (91% identical), dog CRTC2 (90% identical), rabbit CRTC2 (71% identical), tropical clawed frog crtc2 (61% identical), Drosophila melanogaster Crtc (24% identical), Caenorhabditis elegans crtc-1 (18% identical). Paralogues in human: CRTC1 (38% identical), CRTC3 (35% identical).
Diseases named in the same sentence as CRTC2 in open-access papers:
CRTC2 is named in the same sentence as 70 diseases in open-access papers, as found by Europe PMC text mining. Sharing a sentence is not in itself a finding about the gene and the disease. The quoted sentences say what the papers report.
Insulin resistance (19 papers, 2013 to 2025). Increased resistance towards insulin, that is, diminished effectiveness of insulin in reducing blood glucose levels. "On the other hand, a long-term Tac treatment (8 weeks) has recently been shown to inhibit CREB-regulated transcription coactivator 2 (CRTC2) signaling that impacts hepatic metabolic homeostasis ultimately causing insulin resistance." (PMID 40495121, 2025). "Studies show that prolonged activation of CRTC2 during insulin resistance contributes significantly to hyperglycemia." (PMID 40955662, 2025). "Disruption of CREB/CRTC2, a key gluconeogenic transcriptional complex, has been shown to ameliorate insulin resistance in mice." (PMID 35017472, 2022). "Persistent activation of CRTC2 in the liver was sufficient to promote hepatic gluconeogenesis, insulin resistance and steatosis." (PMID 32020874, 2020). "The role of ER stress in diabetes has been well established, and specific roles in liver, adipose and skeletal muscle insulin resistance have also been described, including the inhibition of CRTC2, which results in hepatic insulin resistance in mice." (PMID 23840313, 2013). "Previous studies have shown that insulin resistance is an early change that is observed in CKD, and is it worsened by ongoing chronic inflammation, CRTC2 significantly contributes to the development of insulin resistance, and disruption of CRTC2 increases insulin sensitivity." (PMID 37884902, 2023). "Several works have revealed that prolonged activation of CRTC2 under insulin resistance might play a critical role in hyperglycemia." (PMID 35017472, 2022). "Our research indicated that QGD may improve insulin resistance via regulating the expression of CRTC2, SIK1, PPP1R3C, PGC-1α, G6PC, PPP1R3G, and SREBP1, which are involved in gluconeogenesis." (PMID 36452137, 2022). "CRTC2 may undergo similar retention in the nucleus as S171 cannot be phosphorylated by AKT under the condition of insulin resistance and augments gluconeogenic gene expression in the liver." (PMID 33672754, 2021). "CRTC2/3 promote insulin resistance via induction of the chemokines CXCL1/2." (PMID 34686752, 2021). "Moreover, CRTC2 contributes to the development of hepatic insulin resistance and steatosis through its effects on hepatic gluconeogenesis." (PMID 32020874, 2020). "Thus, hepatic Sam68 potentiates CREB/CRTC2-mediated glucose production, contributes to the pathogenesis of insulin resistance, and may serve as a therapeutic target for T2D." (PMID 36232770, 2022). "Previously, Creb co-activator Crtc2 was shown to be essential in the regulation of chronic activation of gluconeogenesis in the liver, and it was suggested that prolonged activation of Crtc2 under insulin resistance might be crucial for hyperglycemia in that setting." (PMID 29192248, 2017). "Genes downregulated in SHBG-stimulated adipocytes included LEP, LEPR, FLST3, CRTC2, and ID3, all of which are known to contribute to obesity-induced inflammation and insulin resistance." (PMID 40532849, 2025). "The DEGs and DELs between the QGL and MOD groups, such as TG, SIK1, PPP1R3C, CRTC2, PGC-1α, G6PC, PPP1R3G, and SREBP1 were found to be relevant to insulin resistance." (PMID 36452137, 2022). "Collectively, these results indicate that the induction of CXCL1/2 by CRTC2/3 in adipose tissue during HFD feeding, contributes in part to the development of insulin resistance." (PMID 34686752, 2021). "In contrast to these effects, our findings demonstrated that the activation of mTOR/S6K signaling by ER stress in skeletal muscle resulted in a decrease in CRTC2 levels, leading to a subsequent reduction in PGC-1α expression, thereby contributing to the development of insulin resistance." (PMID 35428325, 2022). "Based on the proposed effects of CRTC2/3 on CXCL1/2 expression and insulin resistance, we evaluated whether depletion of CRTC2/3 in adipose tissue modulates the effects of HFD on insulin signaling and glucose metabolism." (PMID 34686752, 2021).
Insulin resistance (continued). "Interestingly, CRTC2 knock down reduced hepatic gluconeogenesis and triglyceride and improved insulin sensitivity in animal models of T2DM and insulin resistance." (PMID 32020874, 2020). "Because of insulin resistance and impaired insulin signaling, patients with obesity and T2DM have low AKT activity and impaired phosphorylation of FOXO1and Crtc2 by AKT, leading to increased FOXO1 and Crtc2 protein levels that drive further gluconeogenic gene expressions." (PMID 36836874, 2023).
Hyperglycemia (14 papers, 2016 to 2025). An increased concentration of glucose in the blood. "The hyperactivation of CRTC2 has been shown to be associated with hyperglycemia in both high-fat diet-induced obese (DIO) and db/db mice." (PMID 35017472, 2022). "In parallel, the CREB/CRTC2 axis modulates insulin sensitivity in the liver and peripheral organs, and dysregulation of the CREB/CRTC2 axis is a major contributor to the hyperglycemia in T2D." (PMID 36232770, 2022). "SMILE is a multifunctional transcription factor that reduces hyperglycemia induced by CREB/CRTC2 signaling and represses adipogenesis by regulating peroxisome proliferator-activated receptor γ (PPARγ)." (PMID 34211461, 2021). "Another showed that FSH enhances gluconeogenesis via CRTC2 and is correlated with fasting hyperglycemia." (PMID 31088900, 2019). "Although CREB-dependent expression of gluconeogenic genes is essential to support glucose production during fasting, it is detrimental in type 2 diabetes, when excessive CREB/CRTC2 complex activity contributes to hyperglycemia." (PMID 28167604, 2017). "We found that the depletion of hepatic Crtc2 is beneficial in relieving not only hyperglycemia but also improving whole-body energy metabolism in diet-induced obesity (DIO) mouse models by promoting an Fgf21-dependent pathway." (PMID 29192248, 2017). "Here, the authors show that the RNA-binding adaptor protein Sam68 promotes the expression level of gluconeogenic genes and increases blood glucose levels by stabilizing the transcriptional coactivator CRTC2, while hepatic Sam68 deletion alleviates hyperglycemia in mice." (PMID 34099657, 2021). "Therefore, the SIK1/CRTC2 signalling pathway will probably represent a novel strategy for suppressing hepatic gluconeogenesis and ameliorating hyperglycaemia." (PMID 31233505, 2019). "Similarly, liver-specific knockout mice for transcription coactivator Crtc2, a regulator of hyperglycemia and lipid metabolism, reduced miR-34a-5p and enhanced SIRT1 expressions under a fatty dietary challenge." (PMID 31500354, 2019). "The significance of this pathway to metabolic homeostasis is underscored by the finding that CREB/CRTC2 activity is highly activated in obese mice, and strategies to inhibit CREB or CRTC2 ameliorate hyperglycemia in obese diabetic animals." (PMID 27336479, 2016). "To determine whether SIK1 overexpression ameliorates hyperglycaemia by decreasing endogenous glucose production in the liver, we measured the mRNA and protein of SIK1, CRTC2, PEPCK and G6pase in the liver." (PMID 31233505, 2019).
Obesity (14 papers, 2016 to 2025). Accumulation of substantial excess body fat. "Human and mouse GULLs ameliorate obesity-induced metabolic abnormalities in a CRTC2-dependent manner." (PMID 40955662, 2025). "We found that Sim1 cell-specific CRTC1 and CRTC2 double-knockout mice were sensitive to high-fat diet (HFD)-induced obesity." (PMID 35020776, 2022). "Having seen that HFD or TNFα treatment increases the nuclear accumulation of CRTC2/3 in adipocytes, we searched for downstream CREB target genes that contribute to the inflammatory and metabolic changes associated with obesity." (PMID 34686752, 2021). "We suggest that Creb/Crtc2 negatively regulates the Sirt1/Pparα/Fgf21 axis via the induction of miR-34a under diet-induced obesity and insulin-resistant conditions." (PMID 29192248, 2017). "To determine whether hGULL and mGULL regulate CRTC2 function, we overexpressed Crtc2 to mimic obesity condition and subsequently expressed hGULL or mGULL to examine their functional interaction." (PMID 40955662, 2025). "CRTC2 is involved in regulating insulin sensitivity, endoplasmic reticulum stress, endoplasmic reticulum stress, viral activation, and obesity, and CRTC2 plays an important role in regulating liver cell gluconeogenesis and maintaining the stability of fasting blood glucose." (PMID 37884902, 2023). "In addition, activation of CRTC genes inhibited lipolysis, which would prevent energy consumption, in turn driving obesity, while the reduction in hepatic CRTC2 expression activated lipolysis, which contributed to the hydrolysis of lipids." (PMID 32020874, 2020). "Given that overexpression of ATF6 in the livers of obese animals seems advantageous in reversing the effects of CRTC2 on the gluconeogenic program, this interaction between ATF6 and CRTC2 may be a significant factor in the impairment of hepatic gluconeogenesis in obesity and type 2 diabetes." (PMID 40145401, 2025). "In addition, mTORC1 signaling acts as a key regulator of the COX-2/PG pathway through the phosphorylation of CREB-regulated transcription coactivator 2 (CRTC2) in adipocytes and has been shown to mediate obesity-induced suppression of COX-2 and beige adipogenesis in WAT." (PMID 31247902, 2019). "Thus, the inhibition of miR-34a by reducing Crtc2 activity in the liver could be beneficial in combating obesity and insulin resistance by promoting whole-body energy metabolism in an Fgf21-dependent manner." (PMID 29192248, 2017). "Without apparent toxicity, APC protects mice from high fat diet-induced obesity, decreases fasting glucose levels, enhances insulin sensitivity and reduces lipid levels in the serum and liver by suppressing CREB/CRTC2-mediated both gluconeogenic and SREBP transcriptions." (PMID 35017472, 2022). "Since CRTC2 whole body knockout mice showed a lean phenotype even in the HFD fed condition, it is likely that the deletion of CRTC2 in PVH would not cause hyperphagia and obesity." (PMID 35020776, 2022). "Another study reported that hepatic mTOR activation in obesity led to the phosphorylation of cytosolic CRTC2 at Ser136, which in turn elicited SREBP1 processing and increased hepatic lipogenesis without any apparent changes in CRTC2 cell localization." (PMID 35428325, 2022).
diabetes (8 papers, 2013 to 2025). "Our observation that the Sam68 deletion lowers blood-glucose levels, and promotes insulin sensitivity by decreasing the stability of CRTC2 protein, suggests that these two molecules may also have a role in the pathogenic mechanisms of diabetes." (PMID 34099657, 2021). "Although more in vivo and clinical studies are required to further solidify our findings, the current study with in vitro experimental results still sheds new light on targeting SIK1 and the CRTC2 signaling for diabetes therapy." (PMID 33013689, 2020). "DPP-4 inhibitor could suppress gluconeogenic gene expression through the inhibition of CREB phosphorylation and CRTC2 expression in mice with diabetes." (PMID 36476135, 2022). "We observed that hepatic Sam68 protein expression is significantly upregulated in diabetic mouse models and in human subjects with diabetes, that glucagon signaling promotes Sam68 translocation from cytoplasm to nucleus, and that Sam68 interacts with CRTC2 both in the nucleus and cytoplasm." (PMID 34099657, 2021). "For instance, the roles of CREB and CRTC2 in diabetes mellitus have been extensively studied, suggesting the involvement of the PAK4-CRTC-CREB pathway in the pathogenesis of diabetes mellitus." (PMID 30755582, 2019). "Elevated amounts of Sam68 and CRTC2 protein, but not mRNA, were also observed in liver tissues from patients with diabetes and were accompanied by a significant increase in both mRNA and protein levels of gluconeogenic genes." (PMID 34099657, 2021). "We began to test this hypothesis by determining whether hepatic Sam68 and/or CRTC2 were upregulated in two commonly used diabetic models, HFD-fed mice, and db/db mice, and in human subjects with or without diabetes." (PMID 34099657, 2021).
type 2 diabetes (5 papers, 2017 to 2025). "This work revealed a mechanism of CREB/CRTC2 that translated into the creation of the novel compound A57, a promising candidate for a new drug to combat type 2 diabetes." (PMID 35017472, 2022). "Polymorphic gene CRTC2 is well known for its critical role in type 2 diabetes, but this polymorphic gene might be responsible for advancement of T1D." (PMID 33827531, 2021).
lung carcinoma (4 papers, 2014 to 2025). "Specifically, CRTC2 accelerates LKB1-deficient lung cancer progression by stimulating ID1 (inhibitor of DNA binding 1) expression." (PMID 40977688, 2025). "Moreover, CRTC2 mutation was validated with a G to A change, resulting in an R379C amino acid change in two lung cancer samples, including two ADCs, with mutation rate of 0.5%." (PMID 24484648, 2014). "The data from the current study demonstrated novel PROM1 and CRTC2 mutations, which could promote lung cancer development." (PMID 24484648, 2014). "In addition, we further verified PROM1 and CRTC2 mutations in an additional 200 pairs of lung cancer and the matched normal tissue specimens." (PMID 24484648, 2014). "In our current study, we found somatic CRTC2 mutation in 7/550 lung cancer patients." (PMID 24484648, 2014). "Current evidence has pointed out oncogenic roles of CRTC2 in lung cancer, consistent with its elevated expression levels in our study." (PMID 34026765, 2021). "We found PROM1 mutation in 3 pairs of lung cancers and normal tissues, including 1 SCC and 2 ADCs with mutation frequency being 1.5% and CRTC2 mutation in 5 pairs of lung cancers and normal tissues, including 3 ADCs and 2 SCCs with mutation frequency being 2.5%." (PMID 24484648, 2014). "We found that mutations of PROM1 and CRTC2 in two lung cancer patients of family cases, but absent in the two healthy members." (PMID 24484648, 2014). "However, it remains unknown what function of CRTC2 protein plays in lung cancer and further studies are warranted." (PMID 24484648, 2014). "Endogenous CRTC1, CRTC2, and CRTC3 proteins showed slow migration patterns in LKB1-expressing lung cancer cells (H322)." (PMID 34142658, 2021).
metabolic syndrome (4 papers, 2016 to 2024). A cluster of metabolic risk factors for CARDIOVASCULAR DISEASES and TYPE 2 DIABETES MELLITUS. "APC was found to prevent metabolic syndrome in obese mice because of its ability to disrupt CREB/CRTC2 interactions." (PMID 37049484, 2023). "APC has been verified to relieve metabolic syndrome in obese mice by blocking the CREB/CRTC2 complex." (PMID 37049484, 2023). "In this work, our results indicate that CREB/CRTC2 is a suitable target for developing anti-metabolic syndrome drugs." (PMID 35017472, 2022). "Pin1 associates with and controls key molecules (IRS-1, CRTC2, AMPK, eNOS, Runx2 and others) involved in metabolic functions or the development of metabolic syndromes." (PMID 27618008, 2016). "Our previous report demonstrated that APC could ameliorate metabolic syndrome by suppressing CREB/CRTC2− mediated gluconeogenesis and the transcription of sterol regulatory element−binding protein (SREBP) in obese mice." (PMID 37049484, 2023). "Artepillin C (APC), a cAMP-response element−binding (CREB)/CREB regulated transcription coactivator 2 (CRTC2) inhibitor isolated from Brazilian green propolis, can ameliorate metabolic syndrome in obese mice." (PMID 37049484, 2023).